GATA6 (GATA binding protein 6)
Diseases named in the same sentence as GATA6 in open-access papers (continued):
Sharing a sentence is not in itself a finding about the gene and the disease.
lung carcinoma (20 papers, 2014 to 2024). "GATA6 was also implicated in the regulation of the chromatin landscape in lung cancer cells, thereby governing tumor proliferation." (PMID 38483616, 2024). "We delineated the pathway underlining the tumor-suppressive function of GATA6 for lung cancer cells." (PMID 32596145, 2020). "We demonstrate that in lung cancer, GATA6 deficiency initially impairs cancer cell proliferation and prevents tumor progression to high-grade lesions." (PMID 32157212, 2020). "Malignancies from endodermal tissues frequently harbor KRAS mutations, and GATA6 expression correlates with KRAS mutations in human lung cancers." (PMID 32157212, 2020). "We show that expression level of GATA6 is higher in para-tumoral tissues than in lung cancer tissues and is significantly associated with better prognosis of NSCLC patients." (PMID 32596145, 2020). "We next investigated the molecular mechanisms underlying the GATA6-induced senescence in lung cancer cell line." (PMID 32596145, 2020). "In this study, we have developed an accurate lung cancer diagnostic test based on the expression analysis of embryonic versus adult isoforms of two genes (GATA6, NKX2‐1) in exhaled breath condensates." (PMID 27821429, 2016). "We assessed GATA6 expression in lung cancer tissues and its association with patient prognosis." (PMID 38483616, 2024). "So, what mechanism underlies GATA6's regulation of the malignant behavior of lung cancer cells?" (PMID 38483616, 2024). "Restoration of GATA6 expression may therefore represent an opportunity for those GATA6-deficient lung cancer patients." (PMID 32596145, 2020). "In human lung cancers, GATA6 is rarely mutated, but its expression is increased in early stage non small cell lung cancer (NSCLC) relative to normal tissue and may correlate with tumor promoting genes." (PMID 32157212, 2020). "Our in vitro data suggested a therapeutic opportunity for GATA6-deficient lung cancer patients: restoring GATA6 in tumor cells may be a treatment option." (PMID 32596145, 2020). "Moreover, the utilization of a c-Myc inhibitor mitigated the proliferation of lung cancer cells induced by GATA6 silencing, concurrently inhibiting the upregulation of mRNA expression of genes associated with glucose metabolism induced by GATA6 silencing." (PMID 38483616, 2024). "In our study, we observed down-regulation of GATA6 expression in lung cancer tissues, with tumors exhibiting lower GATA6 expression levels showing a propensity for larger tumor volumes and lymph node metastasis." (PMID 38483616, 2024). "Conversely, another study has demonstrated that elevating GATA6 levels enhances autophagy, fostering the progression of chemotherapy resistance in lung cancer cells." (PMID 38483616, 2024). "The overexpression of GATA6 hindered the uptake and utilization of glucose by lung cancer cells, whereas decreased GATA6 expression promoted glucose uptake and utilization." (PMID 38483616, 2024). "Among the six family members, GATA6 exhibited the strongest correlation with the prognosis of lung cancer patients, implying a more pronounced involvement of GATA6 in the context of lung cancer." (PMID 38483616, 2024). "In summary, our study has revealed that GATA6 exhibits decreased expression in lung cancer tissues, and its expression levels bear significance in predicting patient prognosis." (PMID 38483616, 2024). "Our findings offer a comprehensive mechanistic insight into how GATA6 regulates the functionality of lung cancer cells, particularly from a metabolic perspective." (PMID 38483616, 2024). "Conversely, in cancer types unrelated to GI, like lung cancer, GATA6 has been shown to inhibit cell migration and proliferation of LSCC cells by downregulating Shh." (PMID 39456519, 2024).
lung carcinoma (continued). "In vitro cell function experiments were conducted to investigate the effects of altered GATA6 levels on lung cancer cell proliferation and migration." (PMID 38483616, 2024). "Our findings revealed that GATA6 overexpression inhibited both glucose absorption and utilization by lung cancer cells." (PMID 38483616, 2024). "Elevating GATA6 levels effectively inhibited the proliferation and migration of lung cancer cells in our cell function experiments." (PMID 38483616, 2024). "Initially, our findings revealed that GATA6 overexpression suppressed the expression of c-Myc mRNA in lung cancer cells, whereas GATA6 underexpression produced the opposite effect." (PMID 38483616, 2024). "Subsequently, our experiments unequivocally demonstrated that GATA6 overexpression significantly inhibited the proliferation and metastasis of lung cancer cells, both in vitro and in vivo." (PMID 38483616, 2024). "Our study revealed significant down-regulation of GATA6 in lung cancer tissues, and this down-regulation was strongly correlated with unfavorable patient prognosis." (PMID 38483616, 2024). "Our study thus provides detailed insights into the specific mechanisms through which GATA6 regulates lung cancer cell functions from a metabolic perspective, offering a robust theoretical foundation for clinical lung cancer treatment." (PMID 38483616, 2024). "To ascertain the functional role of GATA6 in lung cancer cells, we generated cell lines with GATA6 overexpression, and our findings revealed a substantial inhibition of both proliferative capacity and clonogenic potential." (PMID 38483616, 2024). "Lung cancer patients with reduced GATA6 expression experienced poorer overall survival and disease-free survival." (PMID 38483616, 2024). "This study aims to explore the role of GATA6 in lung cancer, with a focus on its impact on metabolic processes." (PMID 38483616, 2024). "The results of IHC also corroborated these findings, indicating lower c-Myc protein expression in lung cancer tissues exhibiting higher GATA6 levels." (PMID 38483616, 2024). "Our cell function experiments also demonstrated that elevated GATA6 expression effectively curtailed the proliferation and migration capabilities of lung cancer cells." (PMID 38483616, 2024). "In our study, we observed a down-regulation of GATA6 expression in lung cancer tissues, and demonstrated its influence on the expression of genes implicated in glucose metabolism by inhibiting C-MYC mRNA." (PMID 38483616, 2024). "Until now, it remains an open and critical question to determine the exact role of GATA6 in the process of lung cancer development." (PMID 32596145, 2020). "Taken together, these data showed that GATA6 exerted TSG function by inducing senescence of lung cancer cells." (PMID 32596145, 2020). "In this study, we uncover a previously unrecognized role for GATA6 during the early stages of lung tumorigenesis and reveal broad epigenomic functions of this lineage factor in lung cancer cells." (PMID 32157212, 2020). "Our recent study showed that QKI-5 negatively regulates miR-196b-5p, and upregulated miR-196b-5p promotes lung cancer cell migration, proliferation, and cell cycle through directly targeting the tumor suppressors, GATA6 and TSPAN12 in NSCLC19." (PMID 32963220, 2020). "GATA6 has also ambiguously been reported to be involved in lung cancer development, with both oncogenic and tumor suppressive roles reported." (PMID 32596145, 2020). "Having confirmed its tumor suppressor function in vitro, we went on to confirm the tumor suppressor function of GATA6 in vivo using transgenic lung cancer mouse model." (PMID 32596145, 2020).
lung carcinoma (continued). "Mesenchymal BMP signaling is required for AT2 differentiation, and the ability of GATA6 to constrain this pathway via multiple gene targets in alveolar-derived lung cancer cells is reminiscent of its role in the colon stem cell niche." (PMID 32157212, 2020). "GATA6 has earlier been reported to exert its TSG function by restricting transdifferentiation of lung cancer cells." (PMID 32596145, 2020). "By combining GEMMs with progenitor-specific gene targeting and integrated epigenomic analysis, we uncovered a novel requirement for GATA6-mediated transcriptional programming in lung cancer." (PMID 32157212, 2020). "The molecular activities of GATA6 during pulmonary specification and lung cancer in particular are not fully understood." (PMID 32157212, 2020). "The aberrant expression or DNA modification of GATA-2, GATA-4, GATA-5, and GATA-6 was found in lung cancer, but GATA-1 gene expression is seldom reported in LADC." (PMID 29100282, 2017). "In addition, studies have found that miR-196b can promote the progression of lung cancer by inhibiting the expression of GATA6." (PMID 38483616, 2024). "Subsequent experimental findings indeed substantiated our hypothesis, demonstrating that GATA6 overexpression effectively suppressed c-Myc mRNA expression in lung cancer cells." (PMID 38483616, 2024). "Notably, the overexpression of GATA6 exhibited the capacity to suppress lactic acid production in lung cancer cells." (PMID 38483616, 2024). "GATA6 can modulate the chromatin landscape of lung cancer cells to control their proliferation." (PMID 38445456, 2024). "Our study provides crucial insights into the metabolic regulation of GATA6 in lung cancer cells." (PMID 38483616, 2024). "Moreover, the overexpression of GATA6 effectively restrained the migratory capabilities of lung cancer cells." (PMID 38483616, 2024). "Our investigation, offering fresh insights into the role of GATA6 from the standpoint of glucose metabolism, furnishes a novel theoretical and empirical foundation with potential implications for the diagnosis and treatment of lung cancer." (PMID 38483616, 2024). "In our investigation, we initiated by analyzing the correlation between GATA6 expression levels and clinical parameters in lung cancer samples, revealing that both mRNA and protein levels of GATA6 were diminished in lung adenocarcinoma tissues relative to normal lung tissues." (PMID 38483616, 2024). "Additionally, statistical analyses conducted using the KMPLOT database corroborated the prognostic significance of GATA6 mRNA expression in lung cancer patients." (PMID 38483616, 2024). "Given the alterations in the metabolic phenotype of lung cancer cells, we sought to determine whether GATA6 expression levels influenced the expression of glucose-related metabolic enzymes." (PMID 38483616, 2024). "GATA6 is negatively regulated in seven sets of lung cancer data and in the PAH set." (PMID 36101460, 2022). "However, GATA6 has been reported to both promote and inhibit cell migration in other types of cancer including lung cancer, suggesting a complex role of GATA6 for this effect." (PMID 36523548, 2022). "Ectopic expression of GATA6 in lung epithelial compartment inhibits lung cancer development." (PMID 32596145, 2020). "Indeed, we confirmed the growth inhibitory effect of GATA6 not only in vitro but also in vivo using a xenograft tumor model and a transgenic mouse model of autochthonous lung cancer." (PMID 32596145, 2020). "Taken together, these data strongly argued that GATA6 was a potent TSG in lung cancer." (PMID 32596145, 2020). "GATA6 overexpression led to senescence of lung cancer cells." (PMID 32596145, 2020). "Moreover, while GATA6 has been implicated in transdifferentiation of NSCLC into liver cancer phenotype, Zito's report suggested that GATA6 can enhance differentiation of lung cancer cells to NSCLC." (PMID 32596145, 2020).
lung carcinoma (continued). "Moreover, GATA6 has been reported to regulate the chromatin landscape of lung cancer cells to modulate the proliferation and divergent lineage dependencies during tumor progression." (PMID 33198372, 2020). "We therefore checked the functional impact of GATA6 on lung cancer development." (PMID 32596145, 2020). "GATA6 aberrant expression is important in several cancers including lung cancer." (PMID 33198372, 2020). "In our current study, we found that GATA6 was a clinically relevant TSG in lung cancer." (PMID 32596145, 2020). "However, we found that the most striking effect of GATA6 expression was on growth of lung cancer cells." (PMID 32596145, 2020). "Combinatorial treatment of retinoids with EGFR-TKIs drugs in EGFR-TKIs resistance lung cancer cells promotes the activation of GATA6 and then inhibits the activation of EGFR/Wnt signaling pathways and favors the association of RXR, RARβ, and cellular retinoic acid binding protein-2 (CRABP2)." (PMID 32293355, 2020). "GATA6 inhibited lung cancer cell growth in vitro and tumorigenesis in vivo." (PMID 32596145, 2020). "We next investigated how GATA6 influenced lung cancer cell growth." (PMID 32596145, 2020). "Our analysis of TCGA data showed that a significant portion of lung cancer samples were GATA6-low." (PMID 32596145, 2020). "Furthermore, GATA6 expression in lung cancer tissues correlated with patient prognosis." (PMID 38483616, 2024). "We then asked whether forced expression of GATA6 inhibited lung cancer development." (PMID 32596145, 2020). "Among the lung cancer cell lines, NCI-H446 (small cell lung cancer cell line) and NCI-H226 (lung squamous cell carcinoma cell line) expressed relatively higher level of GATA6, while the rest were relatively lower." (PMID 32596145, 2020). "In lung cancer, GATA2 and GATA6 were significantly downregulated genes in 17 and 15 studies, respectively." (PMID 30872657, 2019). "The following literature review confirmed that six of the nine TFs, including E2F8, MEIS, E4F1, BRCA1, GATA6, and IRX2, play essential roles in lung cancer progression." (PMID 29303984, 2018). "The results showed that four genes (GATA6, CRISPLD2, CFTR2 and CLPTM1L) have been proven to be involved in lung cancer." (PMID 26183581, 2015). "Similarly, research on GATA6 has revealed its oncogenic role in non-small cell lung cancer (NSCLC) by reducing cell autophagy and cell viability in the H1650 cell line, while in lung cancer it inhibits cell growth in vitro and tumorigenesis in vivo." (PMID 39456519, 2024). "In addition, mRNA isoforms of GATA6 (GATA-binding factor 6) and NKK2-1 (NK2 homeobox 1) in EBC have been proposed for lung cancer detection." (PMID 33572343, 2021). "Furthermore, we observed a negative correlation between the expression levels of GATA6 and c-Myc in lung cancer tissue samples." (PMID 38483616, 2024). "Moreover, GATA6, in synergy with HOPX, regulated overlapping alveolar differentiation and the expression of aggressive target genes, collectively limiting the metastatic potential of lung cancer cells." (PMID 38483616, 2024). "Moreover, GATA6 exhibited no significant impact on lung cancer cell proliferation in a sugar-free medium, underscoring its primary role in regulating glucose metabolism." (PMID 38483616, 2024). "FOXF1 and GATA6 stand out since they are deregulated in the majority, eight and seven, respectively, of the ten sets of lung cancer, in none of the others types of cancer, and in the PAH set, which suggests their association with the establishment of tumor pathology in the lung." (PMID 36101460, 2022).
lung carcinoma (continued). "Furthermore, a negative correlation between GATA6 mRNA and C-MYC mRNA levels was discerned in lung cancer tissue samples." (PMID 38483616, 2024).
colon carcinoma (19 papers, 2008 to 2025). "Interestingly, we found that the exogenous expression of miR-196b in HCT116 colon cancer cells, despite causing a detectable decrease in GATA6 protein levels, slightly increases cell proliferation and, initially, the fraction of mitotic cells." (PMID 27902469, 2017). "REG4 operates downstream the transcription factor GATA6 and has shown potent mitogenic and pro-metastatic effects in gastric and colon cancers." (PMID 39632825, 2024). "In colon cancer, GATA6 overexpression regulates the expression of the urokinase-type plasminogen activator (uPA) gene, which contributes to colorectal tumorigenesis and tumor invasion." (PMID 36691432, 2023). "High levels of Foxa1 expression were observed in poorly differentiated colon cancer, and Gata6, the colon homolog of Gata4, participates in the regulation of stemness by preventing Bmp4-induced differentiation in Wnt-driven colon cancer." (PMID 33349639, 2020). "Gata6 is overexpressed in a variety of cancers, including pancreato‐biliary cancers, colon cancers, esophageal adenocarcinomas, breast cancers, and adrenal tumors." (PMID 30886049, 2019). "Its upregulation was found to correlate with early stages of disease progression and with a marked reduction in GATA6 expression in colon cancer samples." (PMID 27902469, 2017). "We thus transfected HCT116 and HT29 colon cancer cells, which express endogenous GATA6, with the mature miR-196b (miR-196b-5p, Ambion), with a control, unrelated miRNA (Ambion), or with the control, opposite strand miR-196b-3p in HCT116 cells." (PMID 27902469, 2017). "Taken together, these results show that the GATA6 3′UTR can be targeted by miR-196b both in murine embryonal carcinoma as well as in human colon cancer cells." (PMID 27902469, 2017). "GATA6 has been shown to be misregulated in colon cancer cells, suggesting a relevant role for GATA6 in the onset and progression of colon cancer." (PMID 27902469, 2017). "We moreover found that the increase of miR-196b correlates with a reduced GATA6 protein expression in colon cancer patients." (PMID 27902469, 2017). "In our previous study, we observed that suppression of GATA6 expression inhibits the growth and tumorigenicity of colon cancer cells in a nude mouse xenograft model." (PMID 26387746, 2015). "We further have previously shown that miR-363 expression is reduced in colon tumors and that its downregulation results in an increase in GATA6 expression, which thereby enhances LGR5 expression." (PMID 26387746, 2015). "Our findings suggest that GATA6 simultaneously induces the expression of genes essential for colon cancer cell growth under adherent conditions (REG4) and genes that promote their clonogenicity (LGR5)." (PMID 26387746, 2015). "In human colon cancer, GATA6 upregulation decreases the expression level of 15-LOX-1." (PMID 36691432, 2023). "However, liver metastatic colon cancer cells can upregulate aldolase B via GATA6, thereby acquiring the ability to metabolize fructose and enhancing the proliferation ability of colon cancer cells." (PMID 33926551, 2021). "Together, these results establish GATA6 as a target of miR-196b in colon cancer cells." (PMID 27902469, 2017). "We next wanted to verify whether the upregulation of miR-196b expression correlated with a reduction in GATA6 expression in colon cancer tissue samples." (PMID 27902469, 2017). "Our results establish GATA6 as a target of miR-196b in colon cancer cells." (PMID 27902469, 2017). "Furthermore, we demonstrate that GATA6-mediated induction of REG4 enhances the growth of colon cancer cells under adherent conditions." (PMID 26387746, 2015). "Furthermore, we demonstrated that the addition of recombinant REG4 to the culture medium partially restores the proliferation of colon cancer cells expressing miR-363 or those in which GATA6 was knocked down." (PMID 26387746, 2015).